DDO (D-aspartate oxidase)
Description:
Selectively catalyzes the oxidative deamination of acidic amino acids. Suppresses the level of D-aspartate in the brain, an amino acid that can act as an agonist for glutamate receptors. Protects the organism from the toxicity of D-amino acids (By similarity). May also function in the intestine (By similarity).
Synonyms: DASOX; DASPO; DDO-1; DDO-2
Tractability: Small molecule: a structure with a bound ligand is known; it belongs to a druggable protein family. PROTAC: ubiquitination databases record sites on it; its protein half-life has been measured; a small molecule that binds it is known.
Target class: Enzyme; Oxidoreductase
Gene: Protein-coding gene on chromosome 6 (110,391,771 to 110,415,862, reverse strand). Ensembl gene ENSG00000203797.
Subcellular location: Peroxisome matrix; Cytoplasm, cytosol; Peroxisome matrix (Isoform DDO-1); Peroxisome matrix (Isoform 3)
Subcellular location (Human Protein Atlas): Cytosol
Pathways (Reactome):
Metabolism: Glyoxylate metabolism and glycine degradation
Protein localization: Peroxisomal protein import
Gene Ontology:
Molecular function: D-aspartate oxidase activity; D-glutamate oxidase activity; FAD binding; protein binding; D-amino-acid oxidase activity
Biological process: D-amino acid catabolic process; nervous system process; aspartate metabolic process; D-amino acid metabolic process; L-amino acid catabolic process; regulation of cell communication
Cellular component: cytosol; peroxisomal matrix; peroxisome
Genetic constraint (gnomAD): Loss-of-function variants: 18 observed, 20.83 expected, observed/expected ratio (o/e) 0.86, 90% interval 0.6 to 1.28. The upper end of that interval is the gene's LOEUF score, 1.28, which puts it in group 5 of 6, group 1 being the genes least tolerant of losing a copy. Missense variants: 429 observed, 439.87 expected, observed/expected ratio (o/e) 0.98, 90% interval 0.9 to 1.06. Synonymous variants: 180 observed, 175.43 expected, observed/expected ratio (o/e) 1.03, 90% interval 0.91 to 1.16.
Homologues: Orthologues: chimpanzee DDO (99% identical), macaque DDO (85% identical), pig DDO (84% identical), rat Ddo (82% identical), mouse Ddo (80% identical), guinea pig DDO (79% identical), dog DDO (73% identical), rabbit DDO (73% identical), tropical clawed frog ddo (59% identical), zebrafish ddo (53% identical), Drosophila melanogaster Daao1 (38% identical), Caenorhabditis elegans daao-1 (37% identical), and 4 more. Paralogues in human: DAO (40% identical).
Diseases named in the same sentence as DDO in open-access papers:
DDO is named in the same sentence as 14 diseases in open-access papers, as found by Europe PMC text mining. Sharing a sentence is not in itself a finding about the gene and the disease. The quoted sentences say what the papers report.
schizophrenia (9 papers, 2017 to 2025). A major psychotic disorder characterized by abnormalities in the perception or expression of reality. "The decrease in D-Asp content was associated with a significant increase (about 25%) in DDO enzyme activity in the DLPFC of schizophrenia patients." (PMID 38641826, 2024). "The first study, performed on a small number of samples (7–10 subjects/diagnosis), revealed reduced d-Asp levels (about 40%) in the post-mortem PFC of schizophrenia-affected patients, linked to significantly increased DDO mRNA levels in the same brain area." (PMID 30459655, 2018). "Based on the NMDAR dysfunction hypothesis, it has been proposed that inhibitors of the human D-aspartate oxidase (hDASPO) could represent a potentially innovative strategy to counteract the loss of response to antipsychotics in schizophrenia." (PMID 35883465, 2022). "Moreover, a single nucleotide polymorphism (SNP) rs3757351 on the DDO gene is also associated with reduced DDO expression in in vivo prefrontal phenotypes relevant to schizophrenia and greater prefrontal gray matter volume." (PMID 34681579, 2021). "Moreover, neurochemical detections in post-mortem brain of schizophrenia-affected patients have shown significantly reduced d-aspartate content in prefrontal regions, associated with increased DDO mRNA expression or DDO enzymatic activity." (PMID 30459655, 2018). "Interestingly, the biochemical analysis pointed out that reduced content of d-Asp in the DLPFC of schizophrenia-affected subjects is associated with an aberrant increase in DDO enzymatic activity." (PMID 30459655, 2018). "Furthermore, to assess the effect of putative alteration of d-Asp metabolism in the human brain, another study reported the association among DDO gene variations, prefrontal DDO mRNA expression and structural/functional prefrontal phenotypes relevant to schizophrenia." (PMID 30459655, 2018). "Neurochemical studies in postmortem brain tissue from schizophrenia patients have reported increased DDO mRNA expression, increased DDO activity and reduced D-aspartate levels in the PFC." (PMID 41008577, 2025). "In DDO knockout mice, increased d-aspartate attenuates phencyclidine-induced schizophrenia-like behaviors." (PMID 34681579, 2021).
autism spectrum disorder (1 paper, 2022). A spectrum of developmental disorders that includes autism, and Asperger syndrome. "We corroborated this hypothesis by reporting the first clinical case of a young patient with severe intellectual disability, thought disorders and autism spectrum disorder symptomatology, harboring a duplication of a chromosome 6 region, including the entire DDO gene." (PMID 35915065, 2022).
gastric cancer (1 paper, 2025). A primary or metastatic malignant neoplasm involving the stomach. "In the training cohort, a prognostic model for gastric cancer was developed using univariate and multivariate Cox regression analyses, along with stepwise regression, incorporating the genes SNCG, MNAT3, DDO, ITGAD, FGF8, and ABCB5." (PMID 41323282, 2025).
Obesity (1 paper, 2022). Accumulation of substantial excess body fat. "For those 12 genes, six of them (DDO, SEPT9, TMEM45B, RXRα, ZNF395 and AHRR) were previously reported to be implicated in the obesity or related diseases and the rest six were novel (PACRG, LINC00494, KLHL4, DTX1, VCX3A and VSTM1)." (PMID 35568907, 2022).
DDO also shares sentences with these, for which no sentence is quoted: tumor (4 papers); amoebiasis (1); cancer (1); dilated cardiomyopathy (1); emotional dysregulation (1); Fanconi anemia (1); Intellectual disability (1); neuropathy (1); psychiatric disease (1); thyroid cancer (1).